G6PD (glucose-6-phosphate dehydrogenase)
Diseases named in the same sentence as G6PD in open-access papers (continued):
Sharing a sentence is not in itself a finding about the gene and the disease.
infection (continued). "Western blotting data showed that the expression of G6PD protein in cells decreased significantly 72 hours after recombinant virus Lv‐spong‐piRNA‐823 infection (P < .01, vs‐uninfected control group or NC control group)." (PMID 32596991, 2020). "While the G6PD is the key enzyme of removing oxidative stress in erythrocytes, the early diagnosis is utmost vital to prevent chronic and drug-, food- or infection-induced hemolytic anemia." (PMID 31294066, 2019). "Moreover, the importance of G6PD deficiency screening in blood donors prior to blood transfusion into a recipient during infection or treatment with an oxidative drug cannot be ignored, since blood transfusion from G6PD deficient donor may lead to adverse consequences in susceptible recipients." (PMID 27880809, 2016). "In G6PD-deficient monocyte cultures, increased DENV2 infected cell rates were detected by flow cytometry until 48 hours post-infection, when peak values were reached." (PMID 24625456, 2014). "Monocytes from G6PD-deficient individuals were infected with DENV2 and infection rate, levels of oxidative species, nitric oxide (NO), superoxide anions (O2−), and oxidative stress were determined and compared with normal controls." (PMID 24625456, 2014). "In G6PD-deficient monocyte cultures, increased DENV2 titers were detected by plaque assay until 48 hours post infection, when peak values were reached." (PMID 24625456, 2014). "pAd-G6PD infection resulted in an approximate 5-fold increase in G6PD expression and activity and about a 60% increase in NADPH level." (PMID 23185302, 2012). "Moreover, Influenza virus PR/8 infection mediates 0.45 ± 0.01 (p = 0.005) and 0.25 ± 0.15 (p = 0.029) fold reduction in G6PD and HO-1 scavenger’s gene expression, respectively." (PMID 37853388, 2023). "G6PD patients are a unique population that is more vulnerable to infections." (PMID 36978361, 2023). "Reduction of the activity of G6PD facilitates infection of human cells by the coronavirus." (PMID 35805067, 2022). "Moreover, the infection decreases the antioxidant response mediated by the Nrf2 pathway and the G6PD enzyme, which is involved in the regeneration of GSH." (PMID 36145282, 2022). "Whether G6PD phosphorylation is activated after infection to promote viral replication still needs further study." (PMID 36091812, 2022). "Sixteen infants had G6PD and 19 were diagnosed with infection (41.3%)." (PMID 34526082, 2021). "Next, to evaluate whether the down-regulation of G6PD expression in infected cells is mediated by a reduction of its transcription factor, both NRF2 and G6PD mRNA and protein levels were analyzed at different times (2-24 h) of infection." (PMID 35071051, 2021). "Interestingly, influenza virus inhibited NRF2 expression within 2 h of infection and induced a subsequent inhibition of downstream antioxidant genes, including G6PD itself." (PMID 35071051, 2021). "Although statistically significant, the OR of 0.36 indicates that the G6PD deficiency does not prevent the contraction of infection." (PMID 30286752, 2018). "Patients with normal glucose-6-phosphate dehydrogenase status with symptomatic P. vivax mono-infection were enrolled and randomly assigned to receive either chloroquine (CQ) or artemether-lumefantrine (AL), alone or in combination with 14 d of semi-supervised primaquine (PQ) (3.5 mg/kg total)." (PMID 28510573, 2017). "This indirectly indicates that G6PD deficiency does not provide absolute immunity against infection with P. falciparum." (PMID 29065882, 2017). "We found that overexpression of G6PD by pAD-G6PD infection restored redox balance." (PMID 23185302, 2012). "When G6PD-deficient patients are infected with DENV, their higher viral load may increase the probability of transmission of the infection to others via infected mosquitoes, if mosquito breeding sites are not properly environmentally controlled." (PMID 18270558, 2008).
infection (continued). "This enzymopathy can be symptomless or can generate severe clinical symptoms such as chronic hemolytic anemia (G6PD variant class A), neonatal jaundice and acute hemolytic anemia generated by some drugs, fava beans, or infection (G6PD variant class B), and no hemolysis (G6PD variant class C)." (PMID 39684266, 2024). "Besides, infection with the influenza virus could decrease glucose-6-phosphate dehydrogenase (G6PD) expression and activity, which exacerbates oxidative stress and replication." (PMID 37124033, 2023). "In addition to its well-known antioxidative activity, G6PD exhibits a pro-inflammatory mechanism of action; activated G6PD may enhance oxidative inflammation in acute lung injury during infection, possibly exacerbating clinical symptoms." (PMID 36905446, 2023). "Kaplan–Meier curves were used to evaluate time to infection, hospitalization, ICU admission, and death by G6PD status." (PMID 41433239, 2025). "The relative mRNA expression levels of Mx1 and TOP1 were significantly upregulated, whereas those of eIF4E, G6PD and PGAM1 were significantly downregulated in PK-15 cells during infection with SVA." (PMID 35632606, 2022). "Thus, although we cannot exclude off-target effects, our data suggest that p300/SIRT2 pathway may contribute to the regulation of G6PD activity during IV infection and suggest G6PD as a potential target to control the redox cell environment in virus-infected cells." (PMID 35071051, 2021). "G6PD deficient children (10.8%) that did not receive primaquine treatment had a significantly higher prevalence (aOR: 1.77, p = 0.01) and increased risk of acquiring new bloodstage infections (molFOB aIRR: 1.51, p = 0.03), underscoring the importance of anti-relapse treatment." (PMID 30922304, 2019). "For the primary outcome, 99·7% (95% CI 99·4–99·8; 4664/4680) of patients with P vivax mono-infection aged at least 16 years were treated or not treated with tafenoquine in accordance with the appropriate G6PD activity." (PMID 38365417, 2024). "The primary endpoint was the proportion of patients aged at least 16 years with P vivax mono-infection treated or not treated appropriately with tafenoquine in accordance with their G6PD status." (PMID 38365417, 2024). "The proportion of patients aged at least 16 years with P vivax mono-infection who were treated or not treated appropriately with tafenoquine in accordance with their G6PD status was 99·7% (95% CI 99·4–99·8; 4664/4680)." (PMID 38365417, 2024). "Notably, G6PD, ACLY, and PGK1 were also detected in our IP-MS analysis of SIRT2 interactions during infection." (PMID 37916830, 2023). "Hemoglobin electrophoresis was normal (HbF 3.3%), G6PD and PK were normal, with no sign of infection, and Coombs test was negative." (PMID 36003639, 2022). "This study examined the mechanism underlying this phenomenon by measuring the expression of antiviral genes—tumor necrosis factor alpha (TNF-α) and GTPase myxovirus resistance 1 (MX1)—in G6PD-knockdown cells upon human coronavirus 229E (HCoV-229E) and enterovirus 71 (EV71) infection." (PMID 26694452, 2015). "Indeed, Nrf2 and G6PD expression, which was found to decrease during the infection, was not restored after the treatment either." (PMID 36145282, 2022). "The molecules did not exert their antioxidant properties during infection; in fact, they were not able to rescue the virus-induced drop in GSH content or improve the antioxidant response mediated by the Nrf2 transcription factor and G6PD enzyme." (PMID 36145282, 2022).
genetic disorder (32 papers, 2005 to 2025). "Glucose-6-phosphate dehydrogenase (G6PD) deficiency is a group of X-linked, hereditary genetic disorders caused by mutations in the G6PD gene and results in functional variants of about 400 biochemical and clinical phenotypes." (PMID 34930507, 2021). "Glucose-6-phosphate dehydrogenase (G6PD) deficiency is a group of X-linked, hereditary genetic disorders caused by mutations in the G6PD gene." (PMID 34930507, 2021). "The activity of alternative pathways provides robustness of NADPH supply and, to some extent, compensates for the deficit of PPP flux in patients with glucose-6 phosphate dehydrogenase (G6PD) deficiency—one of the most common genetic diseases in humans." (PMID 32033390, 2020). "The main drawback of PQ use is dose-dependent acute haemolysis in glucose-6-phosphate dehydrogenase (G6PD) deficient individuals, a sex linked genetic disorder." (PMID 27287612, 2016). "Glucose-6-phosphate dehydrogenase (G6PD) deficiency, or “primaquine sensitivity”, is the most common genetic disorder with an estimated 400 million people affected worldwide." (PMID 26226515, 2015). "Glucose-6-phosphate dehydrogenase (G6PD) deficiency is a genetic disorder that results in an inadequate amount of G6PD enzyme, a biological catalyst that is important to produce the reduced form of nicotinamide adenine dinucleotide phosphate that protects red blood cells against oxidative stress." (PMID 37388931, 2023). "Glucose-6-phosphate dehydrogenase (G6PD) deficiency is the most common genetic disorder in humans." (PMID 25536053, 2014). "Glucose-6-phosphate dehydrogenase (G6PD) deficiency and haemoglobins S (HbS) are common genetic disorders in sub-Sahara Africa." (PMID 25470251, 2014). "Deficiency of G6PD is an inherited genetic disorder, X-linked and recessive, in which a G6PD gene mutation leads to inefficient or absent expression and a corresponding deficiency of the enzyme." (PMID 37376524, 2023).
blood disorders (27 papers, 2005 to 2025). "Glucose 6-phosphate dehydrogenase (G6PD) deficiency is the most common hereditary blood disorder, affecting millions of people worldwide." (PMID 36419023, 2022). "The co-existence of the HbS allele and the G6PD mutation in the setting of Guinea Bissau is important for phenotypic variability of hematological diseases." (PMID 35463879, 2022). "Caution must also be exercised in patients with impaired renal function, impaired hepatic function, severe drug allergies, glucose-6-phosphate dehydrogenase deficiency or blood dyscrasias." (PMID 15726101, 2005). "Haematological disorders have been frequently noticed as secondary findings, including G6PD (NM_000402.3):c.653C>T (OMIM 300908), HBB (OMIM:613985) and (OMIM: 603903)." (PMID 37799141, 2023). "The hemoglobin concentration results provided by the STANDARD G6PD Test were also evaluated against a reference assay in both the blood disorder study and the US clinical studies." (PMID 34543346, 2021). "The results of the STANDARD G6PD Test were compared to those of the reference assay across a panel of blood specimens with a range of blood disorders and other potential endogenous interferents." (PMID 34543346, 2021). "The performance of the STANDARD G6PD Test was evaluated at a specialized hematology laboratory in London, United Kingdom, on multiple common blood disorders and across a broad range of hemoglobin concentrations." (PMID 34543346, 2021). "This protein is important for the maintenance of redox homeostasis, and a lack of G6PD has been implicated in several hematological disorders." (PMID 36142365, 2022). "Additionally, the measurement of the level of knowledge based on the overall mean score of the participants is one of our study limitations, which resulted from the use of the Jazan study questionnaire, where similar prevalence trends of G6PD and hematological diseases are found." (PMID 38125694, 2023). "It is interesting to note that among 31 children of the 175 otherwise healthy children in the 1st grade, there was a G6PD blood disorder and none of them had refractive error." (PMID 21180428, 2010). "For the 28 blood specimens with a WBC count of > 30 x 109 cells/L included in the blood disorder study, it was possible to assess the impact of high WBC count on both the reference and point-of-care tests through depletion of the WBCs and measuring G6PD activity prior to and post depletion." (PMID 34543346, 2021).
metabolic disorders (16 papers, 2011 to 2025). "Glucose-6-phosphate dehydrogenase (G6PD) deficiency is one of the most common inherited metabolic disorders in humans with highest frequencies found in African, South Asian, Middle Eastern and Mediterranean populations." (PMID 26688730, 2015). "Glucose 6-phosphate dehydrogenase (G6PD; EC 1.1.1.49) and pyruvate kinase (PKLR; EC:2.7.1.40) deficiencies are the most common hereditary metabolic disorders affecting red blood cells." (PMID 36038921, 2022). "Effect of kinetic parameters on over all cellular functions of G6PD and PK genes due to change in single nucleotide polymorphism related to human RBC metabolism disorders have already been done." (PMID 21931771, 2011). "As an excellent intervention in metabolic diseases, exercise increases the level of peroxisome proliferator-activated receptor γ coactivator 1α (PGC-1α) which promotes G6PD transcription and higher intramyocellular lipid (IMCL) content in skeletal muscles." (PMID 32582032, 2020). "Hence, PPP enzymes such as G6PD, including 6PGD and TKT, are promising targets for the treatment and anticipation of metabolic diseases." (PMID 34827081, 2021).
infectious disease (15 papers, 2015 to 2026). A disorder directly resulting from the presence and activity of a microbial, viral, or parasitic agent in humans. "Similarly, it was shown that G6PD-deficient individuals have a higher incidence of infectious diseases, indicating a predisposition to infections." (PMID 38068806, 2023). "The first included only participants who had been screened for infectious diseases at the time of G6PD testing, aiming to minimize potential bias related to transient alterations in enzymatic activity." (PMID 41433239, 2025). "G6PD-deficient patients, similar to individuals with ADHD, exhibit a higher incidence of infectious diseases worldwide, indicating a vulnerability to infections." (PMID 38068806, 2023). "We evaluated the G6PD status and infectious disease screening tests of 1001 adult male Cameroonian blood donors (mean age 31.7 ± 9.8 years)." (PMID 30940186, 2019). "Characterization of quantitative G6PD phenotype in a large population of females has never been carried out before and represents a resource for informing treatment for several infectious diseases in women living in an endemic area." (PMID 29181452, 2017).
cardiovascular disease (12 papers, 2016 to 2024). "Recently, G6PD has been implicated in several inflammatory diseases, such as cardiovascular disease, celiac disease and asthma." (PMID 36829893, 2023). "Multiple studies have shown that G6PD deficiency increases the risk of cardiovascular disease, which implies that G6PD may act as a regulator of SMCs." (PMID 36091812, 2022). "Early intervention may reduce the risk of cardiovascular disease in the susceptible G6PD deficient population." (PMID 33050491, 2020). "It is important to note that G6PD could play opposite roles in different tissues; low G6PD in erythrocytes leads to higher hemolysis but slightly lower than normal G6PD activity was shown to be associated with lower risk of cardiovascular disease." (PMID 30161219, 2018). "We also observed higher expression of G6PD, required for FA and cholesterol biosynthesis, and a lower expression of atheroprotective APOH in 13-HPODE-treated cells compared to LA-treated cells, which could propose a mechanism by which LOOHs contribute to the development of cardiovascular disease." (PMID 33546321, 2021).
bacterial infection (7 papers, 2013 to 2024). "One study reported that patients with the G6PD Mediterranean mutation showed a more severe clinical course during bacterial infection compared to patients with wild type G6PD." (PMID 30601843, 2019). "In conclusion, we demonstrate a cell damage mechanism in G6PD-deficient epithelial cells upon bacterial infection." (PMID 24223971, 2013). "Here, we demonstrate that a lower cell viability was observed among G6PD-deficient cells when compared to scramble controls upon bacterial infection using the MTT assay." (PMID 24223971, 2013). "A higher expression level of the intrinsic apoptotic initiator caspase-9, as well as the downstream effector caspase-3, was detected by Western blotting analysis of G6PD-deficient cells following bacterial infection." (PMID 24223971, 2013). "A more significant accumulation of ROS production in G6PD-deficient cells than in control scramble cells (P < 0.05) was observed upon bacterial infection." (PMID 24223971, 2013). "Our study demonstrates a direct impact of bacterial infection on G6PD-deficient epithelial cells, a result that is in contrast to that found in blood cells." (PMID 24223971, 2013). "In conclusion, we propose that bacterial infection, perhaps the secreted S. aureus α-hemolysin in this case, promotes the accumulation of intracellular ROS in G6PD-deficient cells." (PMID 24223971, 2013). "In the present study, we investigate the direct impact of bacterial infection on G6PD-deficient epithelial cells using Staphylococcus aureus as a model pathogen." (PMID 24223971, 2013). "G6PD deficient granulocytes in G6PD Mediterranean variant displayed reduced function by 25% to 33% in most studies, suggesting an increased susceptibility to bacterial infection." (PMID 27467818, 2016). "We are interested in studying the impact of bacterial infection in G6PD-deficient cells." (PMID 24223971, 2013). "We further highlight a much worse outcome in G6PD-deficient cells upon bacterial infection." (PMID 24223971, 2013). "We hypothesized that G6PD-deficient cells are less tolerant to oxidative stress upon bacterial infection, leading to the accumulation of more intracellular ROS when compared to the control scramble cells." (PMID 24223971, 2013). "Therefore, we propose that cells with G6PD deficiency may be less tolerant to the oxidative stress caused by bacterial infection." (PMID 24223971, 2013). "In fact, the activity of glucose-6-phosphate dehydrogenase, which is the rate-liming enzyme for the pentose phosphate pathway, seems to be closely related to the activation of the inflammasome in response to bacterial infections." (PMID 38281064, 2024).
neurodegenerative disease (5 papers, 2019 to 2024). A disorder of the central nervous system characterized by gradual and progressive loss of neural tissue and neurologic function. "Glucose-6-phosphate dehydrogenase, the rate-limiting enzyme in the pentose phosphate pathway, is highly active in the brain and its dysregulation has been implicated in neurodegenerative diseases." (PMID 38960035, 2024). "Increasing G6PD activity increases longevity in Drosophila and mitigates the effects of neurodegenerative disease." (PMID 38204362, 2024). "G6PD overexpression has also been used to ameliorate the effects of neurodegenerative disease in Drosophila." (PMID 38204362, 2024). "However, in neurodegenerative diseases, the efficaciousness of G6PD is controversial due to its dual role as antioxidant and a ROS generator." (PMID 33222382, 2020).
retinopathy (5 papers, 2020 to 2026). "Patients who were pregnant and breastfeeding and those with contraindications to chloroquine such as retinopathy, QT prolongation, and deficiency of glucose-6 phosphate dehydrogenase (G6PD) enzyme were excluded from the study." (PMID 32542131, 2020). "Individuals with G6PD A- variant rs1050828-T had a higher risk of retinopathy than those without the deficiency at the same HbA1c levels." (PMID 41575919, 2026).
heart disease (4 papers, 2007 to 2024). "Glucose-6-phosphate dehydrogenase (G6PD) is the rate-controlling enzyme of the pentose phosphate pathway, which is reported to be implicated in heart disease." (PMID 26944061, 2016). "The upregulation of myocardial G6PD provides sufficient NADPH and fuels the superoxide-producing enzymes, suggesting a redox role for G6PD in the pathogenesis of heart disease." (PMID 31500396, 2019).